MDM4 (MDM4 regulator of p53)
Diseases named in the same sentence as MDM4 in open-access papers (continued):
Sharing a sentence is not in itself a finding about the gene and the disease.
cancer (continued). "Therefore, further investigation of the relationship between PRPF19 and MDM4 in cancer cells would contribute to improvements in cancer diagnosis and therapy." (PMID 34144037, 2021). "Amplification of MDM2 or MDM4 genes in some cancers results in decreased patient survival." (PMID 34572735, 2021). "Together, these observations strongly indicate that MDM4 is a promising target for cancer therapy." (PMID 34144037, 2021). "Accordingly, a recent report indicated that high levels of MDM4 may support the therapeutic application of anti-cancer ferroptosis inducers independently of p5318." (PMID 34052831, 2021). "Dysregulation of MDM4 has been detected in different cancer types and various mechanisms may promote its upregulation." (PMID 33429878, 2021). "MiR-1205 serves as a cancer suppressor by disengaging the interplay of MDM4/E2F1 and KRAS in NSCLC." (PMID 33589572, 2021). "MDM4 upregulation has been reported in various human cancers." (PMID 33429878, 2021). "MDM4 rs4245739 was intensively studied in different types of cancer." (PMID 32492903, 2020). "We wanted to test the possibility that continuous CDK9 activity could be required to maintain MDM4 expression also in non-cancer cell types." (PMID 32934219, 2020).
cancer (continued). "Together, these data pointed out that MDM4 acted as a cancer‐promoting gene in NSCLC cells." (PMID 33146951, 2020). "Importantly, MDM4 mRNA levels are elevated in numerous cancers, and while altered copy number is responsible for this in some cancers, altered post-transcriptional events have emerged in others." (PMID 30689920, 2019). "It raises questions of whether specific MDM4 promoters dominate in cancer and the ramifications for therapy." (PMID 30689920, 2019). "It is worth noting that while particular interest has focused on distinguishing MDM4-FL from MDM4-S in cancers, such as those of the breast, this work from the Jochemsen group would predict that more precise discrimination between the 75-kDa and 76-kDa forms in cancer would be extremely pertinent." (PMID 30689920, 2019). "Importantly, the dysregulation of MDM4 has significant impacts on multiple hallmarks of cancers, often resulting in compromised tumor suppression and cancer development." (PMID 30689920, 2019). "Any insight would be important for any cancer type that CTNNB1 or MDM4 plays a physiological role." (PMID 29362363, 2018). "In the following section, we will discuss a recent set of data suggesting that targeting Mdm4 splicing might be a promising strategy against cancer cells." (PMID 28230750, 2017). "In addition, an increase in MDM4-S/MDM4 ratio has been proposed as a marker of poor prognosis in different human cancers." (PMID 28460439, 2017). "Even if targeting MDM4 splicing might be a promising anti-cancer strategy, two important issues must be anticipated and addressed." (PMID 28230750, 2017).
cancer (continued). "Further, MDM4 overexpression and amplification have been observed in several cancer forms." (PMID 26867771, 2016). "Although the observed ORs are too low to argue for any clinical use of MDM4 SNP status, further studies are warranted in order to reveal whether it could be a useful marker in any subgroup of cancers." (PMID 26867771, 2016). "Numerous studies have investigated the association between this MDM4 polymorphism and cancer risk, but have failed to reach a definitive conclusion." (PMID 27687591, 2016). "We also identified MDM4 as a cancer amplified gene with potential cancer driver activity." (PMID 24874471, 2014). "The gene MDM4 has become a target of interest for therapeutic intervention in cancer." (PMID 22870278, 2012). "Interestingly, inactivation or loss of RPL22 in cancer is associated with increased expression of RPL22L1 and inclusion of exon 6 in MDM4, an event that promotes MDM4 expression by preventing formation of a ‘short’ MDM4 mRNA isoform (MDM4s) that is destroyed by nonsense-mediated decay." (PMID 38682900, 2024). "Furthermore, some tumors overexpress specific cancer genes located on 1q (e.g., MDM4, ABL1, MCL1) indicating that these patients might benefit from targeted therapies in the future." (PMID 36230794, 2022). "Furthermore, FLT1 of LUSC, ITGB1 of DLBC, MDM4, and CDKN1A of ACC, MAPK1, and ERBB3 of UCEC, FGFR1 of ESCA, and EREG and BCL2L1 of COAD have been strongly associated with patient survival in their respective cancers." (PMID 34079798, 2021). "Consequently, blocking MDM2 and MDM4 has been proposed as a cancer treatment strategy." (PMID 33669778, 2021). "Dysregulated MDM4 splicing has been linked to cancer, but not without controversy." (PMID 30689920, 2019). "However, expression of MDM4 was significantly lower in both cancer tissues than in normal tissues." (PMID 27659536, 2016). "In this case-control study, we aimed to evaluate the possible association between MDM4 SNP34091 status and cancer risk by comparing the genotype frequencies in large hospital-based cohorts of endometrial- (n = 1404) and ovarian (n = 1385) cancer patients with healthy female controls (n = 1870)." (PMID 26867771, 2016).
cancer (continued). "Thus, the somewhat variable results regarding MDM4 SNP34091 and cancer risk may also be explained by yet unknown functional SNP (s) that are in linkage disequilibrium (LD) with SNP34091." (PMID 26867771, 2016). "After full text review, 73 articles were excluded for the following reasons: review articles, duplicate studies, non-case-control study design, genotype distributions were not available, or no evaluation of the association between MDM4 rs4245739 A > C polymorphism and cancer risk." (PMID 27687591, 2016). "Our results elucidate that the MDM4 rs4245739 polymorphism contributes to susceptibility of ESCC and support the hypothesis that genetic variants, interrupting miRNA-mediated gene regulation, may modify cancer risk." (PMID 23724042, 2013). "The MDM4 polymorphism did not have a significant effect on risk of developing cancer because it was not significant in unadjusted (P = 0.1054) or adjusted univariable analysis (P = 0.1584) or multivariable analysis (P = 0.0712) of raw plus inferred genotype data." (PMID 20520810, 2010). "ACIN1 and SYNE2 showed a combined effect with ESR2 on either OS or DFS in 9 out of 17 cancer types, TNFRSF13C showed a combined effect with ESR2 in 8 cancer types, and MDM4 showed a combined effect with ESR2 in 7 cancer types." (PMID 39201394, 2024). "The 1q+ tumors of EX3 share overexpression of seven cancer genes e.g., BCL9 and SETDB1, whilst EX1 1q+ tumors share only MDM4 overexpression and overexpress fewer cancer genes overall." (PMID 36230794, 2022). "MDM4 (also known as MDMX) is the only MDM2 homolog that is expressed at levels higher than MDM2 due to its increased expression and protein stability in most cancer types." (PMID 36431769, 2022). "Genes such as EGFR, PIK3CA, DROSHA, MDM4, and APC were located inside recurrently aberrant regions, while other known cancer-genes such as NF1, MET and mTOR were identified as cis-genes and located outside the most recurrently altered regions." (PMID 34625038, 2021).
cancer (continued). "Hub nodes such as MDM4, ZNF410, AC0842-19, and CTB-89H12 were differentially expressed between cancer and normal sample in different subtypes and tumor stages." (PMID 32802855, 2020). "In cancer cells, p73 transcription activity is abrogated, among other mechanisms, by binding to MDM2 or MDMX (human MDM4)." (PMID 30603043, 2018). "Recently, the relative expression of MDM2, MDM2-B, MDMX (MDM4), and MDMX-S has been found to predict heterogeneous responses of Nutlin-3 in cancer cells." (PMID 27129163, 2016). "Among them, the following well-known cancer genes were found: MET, CDK4, MDM4, EGFR and PIK3CA (amplifications), and CDKN2A, MLLT3, HRAS, CARS and NF1 (deletions)." (PMID 23408991, 2013). "In addition, we examine other relevant receptors, such as MDM4 and BCL2, for their potential inhibitory effects to restore tumor-suppressive functions, ultimately contributing to improved cancer therapies." (PMID 40733263, 2025).